ATM (ATM serine/threonine kinase)
Diseases named in the same sentence as ATM in open-access papers (continued):
Sharing a sentence is not in itself a finding about the gene and the disease.
colorectal cancer (continued). "In this review, we provide an overview of mechanisms, preclinical studies and advances in clinical trials of DNA-PKcs, ATM/ATR, CHK1/CHK2, WEE1 and PARP1 kinase inhibitors combined with radiotherapy for colorectal cancer treatment." (PMID 36230796, 2022). "We used this platform to test the response of SW620 colorectal cancer spheroids to irinotecan (SN38) alone and in combination with the ATM inhibitor AZD0156, using concentrations mimicking mouse plasma exposure profiles of both agents." (PMID 34429505, 2021). "For this purpose, we analysed ATM protein expression by immunohistochemistry (IHC) in human NSCLC and colorectal cancer (CRC) specimens." (PMID 27602502, 2016). "In this study, we examined the expression of g-H2AX, ATM and Ku70 in a set of 908 stage II/III colorectal cancers." (PMID 23154512, 2012). "To further investigate the possibility to take advantage of DDR to target acid-exposed cancer cells, we next examined the phosphorylation of ATM and ATR, and downstream checkpoint kinases CHK1 and CHK2 in colorectal cancer HCT116 cells cultured at pHe 6.5 or pHe 7.4." (PMID 38366255, 2024). "To investigate the exact regulatory role of PPP2R5A and the overall process of irinotecan‐activated ATM/ATR signalling, including phosphorylation and dephosphorylation, we exposed colorectal cancer cells to irinotecan for 1 h and then left the cells to recover for different time." (PMID 35187743, 2022). "The colorectal cancer cell line SK-CO-1 lacking detectable ATM protein expression has been shown to be sensitive to the PARP inhibitor olaparib, similar to HCT116 cells following siRNA-mediated depletion of ATM." (PMID 33224881, 2020). "We found that there was inconsistency in the frequency distribution of CNAs in both of the data sets for those actionable genes from our list which are considered promising druggable targets for NSCLC, and colorectal cancer, such as KRAS, BRAF, EGFR, ATM, and PIK3CA." (PMID 30728399, 2019). "Without a functional MRN‒ATM complex, downstream regulation of DDR is impaired, resulting in significant susceptibility to colorectal cancer." (PMID 30769804, 2019). "Among the 46,588 tumor samples in the “curated set of nonredundant studies”, ATM and ATR are mutated in many different cancer types with the frequency ranging from ~1% for brain or testicular cancer to ~8–10% for endometrial, bladder, or colorectal cancer." (PMID 33742106, 2021). "We performed a more detailed analysis on a few selected cancer types: for ATM, we chose colorectal cancer, endometrial cancer, and non-Hodgkin’s lymphoma because each has a comparable number of mutated residues that are conserved in Mec1 and/or Tel1, 54, 54, and 55, respectively." (PMID 33742106, 2021).
glioma (112 papers, 2008 to 2026). A benign or malignant brain and spinal cord tumor that arises from glial cells (astrocytes, oligodendrocytes, ependymal cells). "The genes implicated in glioma risk play roles in DNA damage response, e.g., ATM, BRCA2, PMS2, POLE, or diverse other processes including metabolism, signal transduction, and cell cycle regulation." (PMID 41546701, 2026). "Specifically, high expression of ATM gene has been shown to be linked with radio-resistance of glioma." (PMID 38666818, 2024). "ATM-deficient human glioma cells were shown to have elevated intracellular ROS levels and to be highly sensitive to ionizing radiation and oxidative stress." (PMID 37296624, 2023). "Loss of ATRX inhibits ATM-dependent DNA damage repair by regulating H3K9me3 modification to increase TMZ sensitivity in gliomas." (PMID 37190157, 2023). "miR-100 overexpression in glioma cells sensitized them to ionizing radiation by downregulating the ataxia telangiectasia mutated (ATM) gene." (PMID 37371047, 2023). "The presence of the IDH1 R132H mutation in glioma is associated with better clinical outcomes through enhancing sensitivity to temozolomide via regulation of the ATM/CHK2 pathway." (PMID 36835465, 2023). "ATM was also associated with immune and metabolic modulators in the response of glioma cells to radiation." (PMID 35158967, 2022). "Additional pathways significantly associated with TRIP13 expression in glioma included “G2/M DNA damage checkpoint” (p = 2.34 × 10−9) and “ATM signaling” (p = 2.95 × 10−7)." (PMID 34066132, 2021). "We investigated the clinical impact of ATM mutations in patients with intracranial IDH-wildtype high-grade glioma undergoing RT following incomplete tumor resection." (PMID 32736562, 2020). "In our own cohort, we found a hypermutated glioma with an inactivating mutation in yet another gene associated with DNA repair, ATM." (PMID 32051040, 2020). "The prevalence of ATM mutations (ATM mut(+)) in high-grade glioma is known to be less than 5%; hence, owing to this rarity, there have been no clinical reports on such patients." (PMID 32736562, 2020). "Owing to the limited number of ATM mutations in high-grade glioma, a further validation in a larger cohort, even including patients under gross total removal status, is needed to identify the prognostic value of ATM mutations." (PMID 32736562, 2020). "Taken together, these results show that high ATM expression in glioma is associated with poor patient survival." (PMID 29348882, 2017). "Additional western blot analysis indicates that ATM knockout also caused significantly reduced expression of Oct4 and Nestin, two important markers of glioma stem cells." (PMID 28337983, 2017). "Our results indicate that ATM and caspase-3 knockout caused significant attenuation in the abilities of glioma cells to grow in immunodeficient mice." (PMID 28337983, 2017). "Dbait32Hc-induced vimentin Ser459 phosphorylation was found in various human cell lines, including MRC-5 (transformed fibroblasts), SK28 (skin melanoma), AT5BI (ATM-deficient fibroblasts) and M059K (glioma) cells." (PMID 24282534, 2013). "Additional pathways significantly associated with EZH2 expression in glioma were "ATM signaling" (p = 2.2E-6), "G2/M DNA damage checkpoint" (p = 1.0E-5) and "Sonic hedgehog signaling" (p = 1.5E-3)." (PMID 20920292, 2010).
glioma (continued). "Our data of heterozygous ATM GVs in 2.9% glioma patients with presumed tumor predisposition corroborate and extend the findings of ATM GVs in 1/152 (0.7%) glioma patients and 3/304 (1.0%) glioma families." (PMID 41546701, 2026). "Preclinical data and retrospective analyses, respectively, suggest that ATM deletions radiosensitize primary gliomas to radiation therapy and that ATM variants may predict local intracranial control after conventional radiation therapy." (PMID 38260227, 2024). "Consequently, the combination of irradiation and ATM inhibitors provides a novel synthetic lethal therapy for ATRX-deficient glioma." (PMID 37190157, 2023). "An association of ATM with the sensitivity of glioma cells to TMZ has been reported, which may be relevant for the combination with RT." (PMID 35158967, 2022). "An example of such an inhibitor used to treat brain tumor cells is NVP-BEZ235, an inhibitor of multiple targets that include ATM and DNA-PK catalytic subunit (DNA-PKcs), which was associated with the increased sensitivity of glioma stem cell xerographs in mice to RT and TMZ." (PMID 35158967, 2022). "The number of café-au-lait macules has been found to be influenced by common SNPs, polymorphisms in ADCY8 correlate with glioma risk in a sex-specific manner, and rare germline variants in various genes including ATM have been proposed as candidate modifiers of plexiform neurofibroma." (PMID 36760809, 2022). "Moreover, ATM inactivating mutations are more frequently described in solid tumors with areas of hypoxia, such as gliomas, thus contributing to radiotherapy resistance." (PMID 34068084, 2021). "In the current study, the ATM mut(+) group was shown to yield excellent in-field control, indicating the radio-sensitive nature of ATM mutations even in patients with intracranial high-grade glioma." (PMID 32736562, 2020). "Four of 6 ATM GVs detected in glioma patients here were LoF variants (two were ClinVar LP/P variants) that resulted in decreased ATM expression in the glioma tissue compared to gliomas from non-ATM GV carriers, thus impacting the molecular phenotype of the tumor." (PMID 41546701, 2026). "Indeed, an association of ATM with the sensitivity of glioma cells to TMZ has been reported." (PMID 35565340, 2022). "Our results demonstrated that ATM mutations might be involved in the increased radio-sensitivity with excellent in-field control despite the aggressive nature of IDH-wildtype high-grade glioma." (PMID 32736562, 2020). "Gliomas from SDHA GV carriers with less DSB accumulation showed a trend towards a higher mean nuclear IRS of RAD51 than those from ATM, BRCA2, and FANCA GV carriers with more DSBs." (PMID 41546701, 2026). "The mean nuclear IRS of PARP1 was significantly higher in gliomas from BRCA2 GV carriers than in those from ATM GV carriers." (PMID 41546701, 2026). "ATRX knockout has been shown to suppress malignant behaviors in glioma cells and plays a critical role in regulating DNA damage repair through the ATM signaling pathway." (PMID 40282990, 2025). "A recent study identified ATM inhibition as a potent radiosensitization strategy in various patient-derived pediatric high-grade glioma models." (PMID 40244686, 2025). "As recapitulated in this analysis, the radiosensitizers investigated in pre-clinical studies for gliomas include ATM, mTOR and PARPis." (PMID 40667051, 2025). "For example, HIF1α was found to orchestrate regeneration resistance by upregulating AMPK-mediated ATM expression in severe hypoxia, while it promotes glioma invasion and stem cell formation by regulating MIR210HG and OCT1." (PMID 38893207, 2024). "Within subtypes of brain cancer, the top three mutation rates were MAD2L2/FANCV (21.49%) in meningioma, XRCC2/FANCU (17%) in rhabdoid tumors, and ATM (16%) in pediatric high-grade gliomas." (PMID 39421870, 2024).
glioma (continued). "For example, HIF1α is involved in promoting radioresistance by modulating AMPK-mediated ATM expression, promoting glioma invasion and stem cell formation via regulating MIR210HG and OCT1, and activating Ror1 transcription to influence cancer progression." (PMID 38893207, 2024). "For instance, PGAM1 has been implicated in the activation of DNA damage repair pathways, as shown in gliomas where it interacts with Wip1, inhibiting its translocation into the nucleus and consequently attenuating the ATM signaling pathway." (PMID 38434965, 2024). "This sleeping-beauty glioma model showed upregulation of the ATM signaling pathway that enhanced DNA damage repair capacity and elicited tumor resistance to radiotherapy." (PMID 37051530, 2023). "As in the case of CHEK2, glioma cell expression of ATM, the upstream activator of CHEK2, also exhibited a T-cell phenotype similar to CHEK2 expression." (PMID 36949040, 2023). "L1 cell adhesion molecule (L1CAM) was shown to enhance the radiation resistance of glioma stem cells by increasing the phosphorylation of ATM and CHK2, slowing down cell death, and improving the formation efficiency and size of GSC tumor spheres." (PMID 37700319, 2023). "Consequent pharmacological inhibition of the ATM pathway restored the tumor’s radiosensitivity, suggesting the translational potential to improve radiotherapy outcomes for patients with IDH1 gliomas harboring similar mutations." (PMID 37051530, 2023). "Glioma biomarkers of predictive value for PARPi therapeutic efficacy include IDH1/2 mutations, a low BRCA1 expression, aberrant ATM or ATR signaling, MYC overexpression, and inactivation of mismatch repair genes, especially MSH6." (PMID 35406593, 2022). "In glioma cells, ATM inhibitors increased radiotherapy sensitivity, with ATM signaling through the RAF/MEK/ERK pathway critical for radiation-induced ATM activation, suggestive of a regulatory feedback loop between ERK and ATM." (PMID 36536316, 2022). "On the other hand, ATM inhibition sensitized GSC to radiation, but differentiation of glioma cells resulted in the loss of the sensitizing effect." (PMID 35158967, 2022). "The ATM inhibitor KU-60019 successfully radiosensitized glioma cell lines, GBM-initiating cells, as well as pediatric high-grade gliomas." (PMID 35158967, 2022). "The increase in ROS can also affect the apoptosis and metabolism of glioma cells via the JNK-regulated metabolic pathway and ataxia telangiectasia mutated (ATM)-Yes-associated protein 1 (YAP1)-driven apoptotic pathway." (PMID 35935861, 2022). "This was consistent with the findings suggesting that ATRX knockout can suppress DNA damage repair by regulating ATM pathway or mediating PARP1 instability to sensitize glioma cells to TMZ treatment." (PMID 35720326, 2022). "In summary, our study revealed that ROCK2 increased HR repair via up-regulating ATM expression in MGMTlow TMZ-resistant glioma cells." (PMID 35145081, 2022). "KU‐60019 is an analogue of KU‐55933 with improved pharmacokinetics and bioavailability and is reported to interrupt radiation‐induced ATM phosphorylation in glioma cells." (PMID 34977872, 2021). "ATM silencing was reported to improve the therapeutic efficacy of DNA damaging agents on glioma cells and mantle cell lymphoma." (PMID 34268251, 2021).
glioma (continued). "Similar to the approach employing a PARP inhibitor targeting BRCA1 mutations in breast and ovarian cancers, several preclinical studies on the inhibition of ATM have been performed to enhance radio-sensitivity in other solid tumors and high-grade gliomas." (PMID 32736562, 2020). "In glioma cells, CD133+ glioma stem cells possessed higher levels of spontaneously induced DSBs and ATM phosphorylation." (PMID 32566127, 2020). "Further studies are necessary to uncover the potential role of ATM as a biomarker and candidate therapeutic target in high-grade gliomas." (PMID 32736562, 2020). "Further preclinical and prospective clinical studies are warranted to elucidate the role of large field RT in patients with ATM mut(+) and the effect of the combination of RT and ATM inhibitors during the course of RT in IDH-wildtype high-grade glioma." (PMID 32736562, 2020). "In this context it has been published that ATM is upregulated in glioma and its inhibition can reduce glioma growth and sensitizes glioma cells towards ionizing radiation and TMZ." (PMID 31354846, 2019). "A synthetic lethal interaction between IDH mutations and PARP inhibition was identified in glioma and AML, and ascribed to decreased ATM expression in AML." (PMID 31810230, 2019). "After examining the ATM methylation status and radio‐sensitivity of 3 glioma cell lines, they observed the same result." (PMID 29952116, 2018). "Afterwards, Boston scholars Roy et al20 researched the role of methylation of the ATM promoter in the radiation sensitivity in glioma." (PMID 29952116, 2018). "AKT activates the ATM signaling and increases the expression of β-catenin, which plays an important role in the formation of glioma radioresistance." (PMID 29246031, 2017). "To demonstrate the functional relevance of the spDSB-induced DDR pathway in the stemness of glioma cells, we examined tumorigenic abilities of the patient-derived glioma cells with caspase-3 or ATM knockout." (PMID 28337983, 2017). "In the second assay, we showed that in both T4121 and D456MG glioma cells, ATM or caspase-3 knockout reduced the ability of the glioma cells to grow in soft agar." (PMID 28337983, 2017). "In the third assay, we evaluated the abilities of the caspase-3 or ATM-knockout glioma cells to form tumors in mice." (PMID 28337983, 2017). "Though never reported for cancer stem cells, the importance of ATM for glioma stem cells is reminiscent of the requirement of ATM in the self-renewal of hematopoietic stem cells." (PMID 28337983, 2017). "Most interestingly, we showed that glioma cell stemness appeared to depend on spDSB-induced ATM activation." (PMID 28337983, 2017). "Our findings of spontaneously arising DSBs driving ATM activation provide a good explanation for the elevated DDR inherent in the glioma stem cells." (PMID 28337983, 2017). "The dependence of glioma stemness on activated caspase-3 and ATM is consistent with requirement of ATM for the self-renewal of hematopoietic stem cells." (PMID 28337983, 2017). "We found that GBM patients with the lowest overall survival had significantly higher levels of ATM expression, and that high-ATM expressing glioma patients had significantly shorter overall survival as compared to low-ATM expressing glioma patients." (PMID 29348882, 2017). "It has been observed that the expression of DDR proteins is higher in glioma than in the adjacent normal tissue and ATM expression levels have been proposed as an independent prognostic factor related to longer survival." (PMID 28587121, 2017). "In glioma cells treated with temozolomide, however, DNA damage activated ATM also signals through AMPK-ULK-1 to promote a protective form of autophagy." (PMID 27903966, 2017).